IL6 (interleukin 6)
Diseases named in the same sentence as IL6 in open-access papers (continued):
Sharing a sentence is not in itself a finding about the gene and the disease.
endothelial dysfunction (continued). "Specifically, the uncontrolled release of pro-inflammatory cytokines such as IL-1β, IL-6, and TNF-α leads to myocardial depression, endothelial dysfunction, and triggers apoptosis pathways in cardiac cells." (PMID 38326366, 2024). "Hs-CRP is an indicator of systemic inflammation, IL-6 can trigger and enhance vascular inflammation and contribute to SAS, and sE-s are indicators of endothelial dysfunction." (PMID 39732653, 2024). "The infection induces a strong inflammatory response, including a cytokine storm (e.g., IL-6, IL-1β, TNF-α), endothelial dysfunction, and microvascular thrombosis, which exacerbate myocardial injury." (PMID 39771983, 2024). "IL-6 also induces ROS production in a NOX2-dependent manner, aggravating endothelial oxidative stress, which in turn sustains endothelial dysfunction." (PMID 39199353, 2024). "Endothelial dysfunction is exacerbated by proinflammatory cytokines such as TNF‐α, IL‐6, IL‐8, and IL‐18, which activate the inflammatory response, induce adhesion molecules like P‐selectin and E‐selectin, and intensify the inflammatory response." (PMID 39040847, 2024). "Earlier studies have focused on endothelial dysfunction-related biomarkers, such as CRP, IL-6, and NLR, which reflect systemic inflammation and are widely reported in various non-central nervous system diseases." (PMID 38539657, 2024). "Inflammatory cytokines, such as interleukin-6 (IL-6) and tumor necrosis factor-alpha (TNF-alpha), promote endothelial dysfunction and accelerate atherosclerotic processes in cerebral and systemic vasculature." (PMID 39735485, 2024). "Pro-inflammatory cytokines, such as IL-6 and TNF-α, are significantly elevated in lung cancer patients and contribute to endothelial dysfunction, plaque instability, and increased coagulation, all of which heighten cardiovascular risk." (PMID 39834733, 2024). "Cytokines such as interleukin-6 (IL-6), tumor necrosis factor-alpha (TNF-alpha), and hormones such as adiponectin (adpN) can directly contribute to endothelial dysfunction by decreasing nitric oxide bioavailability and increasing pro-inflammatory adhesion." (PMID 38571360, 2024). "Endothelial dysfunction (expressed as FMD%) was correlated with focus score, ESSDAI, levels of anti-SSA and anti-SSB antibodies, beta-2 microglobulin, IL-6, and TNF-α, with statistical significance." (PMID 37762225, 2023). "LOX-1 and IL-6 markers are increased in the presence of oxidative stress and inflammation in HMEC-1, thus resulting representative of endothelial dysfunction." (PMID 37372038, 2023). "Adipose tissue is an active endocrine organ that produces several pro-inflammatory cytokines, including interleukin-6 (IL-6) and tumor necrosis factor-alpha (TNF-α), which can promote endothelial dysfunction and vascular remodeling." (PMID 37416924, 2023). "Increased NC has also been correlated with increased markers of inflammation (interleukin 6 [IL-6], tumor necrosis factor-alpha [TNF-alpha], C3, C4) and endothelial dysfunctions (E-selectin)." (PMID 37123795, 2023). "It is confirmed in endothelial cells that LPS induces ER stress and overproduction of IL-6 and MCP-1 through IRE1α/NF-κB pathway, resulting in endothelial dysfunction." (PMID 36204587, 2022). "The results of previous studies demonstrated a positive relationship between circulating ADMA levels and IL-6 and CRP levels, indicating that inflammation and endothelial dysfunction are two parallel processes." (PMID 35330470, 2022). "The activated ACE2-Ang II axis can trigger macrophage infiltration and induce the secretion of several cytokines, including IL-6, CCL2, VCAM-1, and E-selectin, which induce endothelial dysfunction and, subsequently, coagulation." (PMID 35464491, 2022). "PCOS per se has been viewed as a state of chronic low-grade inflammation with increased production of specific cytokines and chemokines such as TNFα, IL-1, IL-6, follistatin, CRP, and adhesion molecules involved in endothelial dysfunction." (PMID 35564864, 2022).
endothelial dysfunction (continued). "Consumption of a single high-fat meal rich in saturated fatty acids can induce endothelial dysfunction in otherwise healthy subjects, as evidenced by the related increased concentrations of VCAM-1, ICAM-1, IL-6, IL-18, and TNF-α." (PMID 35268723, 2022). "Systematic inflammation and circulating cyto- and chemokines including C-reactive protein, IL-6, IL1β, and TNFα fuel CVD through endothelial dysfunction, altered vascular tone, enhanced plaque formation, and coagulation." (PMID 36564799, 2022). "IL-6 and TNF-α are considered potent oxidative stress-inducing agents, thus leading to endothelial dysfunction." (PMID 36009796, 2022). "IL-6 also triggers hepatic synthesis of CRP, while TNF-α is more involved in the activation of inflammatory cytokine, endothelial dysfunction and induction of bone resorption." (PMID 33676486, 2021). "IL-1β, IL-6, and ICAM-1 are important proinflammatory molecules, which play crucial roles in the preliminary inflammatory response and endothelial dysfunction." (PMID 34221236, 2021). "The inflammatory phase that leads to endothelial dysfunction is initiated by TNF-α and subsequently amplified by IL-1, IL-6 and downstream mediators." (PMID 33868242, 2021). "As a result, a cascade of pro-inflammatory markers including IL-1β, IL-6 and TNF-α were upregulated, eventually leading to endothelial dysfunction, as displayed by EDR impairment." (PMID 40477401, 2021). "The MOEDs sICAM-1, P-Selectin, Il-6 and MCP-1 were higher in vWD patients compared to healthy controls in this study which would also possibly indicate more endothelial dysfunction." (PMID 33448867, 2021). "Highly significant positive correlations were shown between serum galectin-3 concentrations and the studied inflammatory markers, including IL-6, PTX-3, and ferritin, and the endothelial dysfunction marker, sFlt-1." (PMID 34439802, 2021). "Unsurprisingly, measures of endothelial dysfunction (E-selectin and ICAM-1) and inflammatory markers (IL-8, IL-6, and IP-10) also demonstrated significant differences between rapid recovery, CCI, and early death groups." (PMID 34535154, 2021). "Vitamin D improves endothelial dysfunction by reducing the oxidative stress of free oxygen radicals, TNF-alpha and interleukin-6 and suppressing the NF-κB pathway." (PMID 34475485, 2021). "As a part of chronic inflammation, endothelial cells are continuously activated by inflammatory stimuli, including IL-6, TNF-α, and IL-1β, resulting in endothelial dysfunction and the progression of fibrosis." (PMID 34202668, 2021). "As a result, proinflammatory cytokines, for example IL-6 and TNF-alpha stimulate neutrophils (PMNs) and monocytes thereby inciting a hyperinflammatory response, vascular leakage, and endothelial dysfunction." (PMID 34457265, 2021). "Meta-analyses reported elevated circulating markers of inflammation, e.g. interleukin 6 (IL-6) and C-reactive protein (CRP), and markers of endothelial dysfunction, e.g. E-selectin, in individuals with SVD." (PMID 34055930, 2021). "Increased RAS activity (renin), endothelial dysfunction (vWF), coagulation parameters (D-dimer, prothrombin fragment F1,2) and inflammation (CRP, IL-6) were significantly altered in COVID patients and followed similar trends from mild-COVID to ARDS-COVID." (PMID 34945736, 2021). "Regarding the inflammatory process and endothelial dysfunction, we also found an increase in proinflammatory cytokines, such as TNF-α and IL-6, which augment monocytes adhesion to endothelial cells." (PMID 32795274, 2020). "Through an LPS model of ARDS, they identified that the production of ceramide and IL-6 in rat PASMCs resulted in failed hypoxic vasoconstriction (HPV), endothelial dysfunction, and hyperresponsiveness to pulmonary vasoconstriction induced by serotonin." (PMID 33537342, 2020).
endothelial dysfunction (continued). "Patients with severe disease have been shown to have increased levels of IL-6, TNFα, MCP1, MIP1A, and IP10, which is also correlated with endothelial dysfunction and increased levels of D-dimer." (PMID 32760409, 2020). "Studies have shown that inflammatory factors IL-6, IL-1β, IL-18, and TNF-α are positively correlated with cardiovascular events and are also involved in the occurrence of endothelial dysfunction." (PMID 33014270, 2020). "Several cytokines have been reported to induce endothelial dysfunction, including TNF-α, IL-6, and IL-1b42." (PMID 32958516, 2020). "Nevertheless, no changes were observed in the concentrations of markers related to endothelial dysfunction [VCAM, E-selectin, and advanced glycation endproducts (AGEs)] or inflammation (hs-CRP, IL-6, and TNF-α)." (PMID 31068933, 2019). "The addition of synthetic peptides to human endothelial cells significantly prevents the expression of genes related to endothelial dysfunction and inflammation (eNOS, ICAM-1, VCAM-1, IL-6) and lowers NF-κB activation (all p < 0.05)." (PMID 31466215, 2019). "Adipose tissue inflammation is induced by intermittent hypoxia and by chronic sleep fragmentation, can result in elevated IL-6 release, and may cross-talk with endothelial cells via adipocyte-derived mediators such as IL-6 to promote NF-κB-dependent endothelial dysfunction." (PMID 30678164, 2019). "High levels of serum inflammatory cytokines and markers such as tumor necrosis factor-α (TNF-α), interleukin-6 (IL-6), C-reactive protein (CRP), and alpha-1-acid glycoprotein (AGP) have been correlated with the endothelial dysfunction." (PMID 31737180, 2019). "Markers of inflammation (IL-6, TNF-α, CRP), innate defense (cathelicidin), monocyte and macrophage activation (sCD14, sCD163 and, IL-2sRα), endothelial dysfunction (ET-1) and general immune health (CD4/CD8 ratio) were associated with lung abnormalities in HIV." (PMID 31830103, 2019). "Inflammatory biomarkers of endothelial dysfunction, such as C-reactive protein (CRP), interleukin-6 (IL-6), intracellular adhesion molecule-1 (ICAM1), and E-selectin, have been widely studied and associated with CSVD in human and animal models." (PMID 31708793, 2019). "To explore the roles of inflammation, endothelial dysfunction, and oxidative stress in normoalbuminuric renal insufficiency, we examined levels of plasma TNF-α, IL-6, ET-1, and 8-OHdG in 209 T2DM patients with normoalbuminuria." (PMID 31637265, 2019). "Pro-inflammatory changes such as increased IL-6 and TNF-α levels are known to trigger acute phase protein responses and increase endothelins exhibiting signs similar to endothelial dysfunction." (PMID 30097052, 2018). "In particular, at a molecular level, MALAT1, by targeting serum amyloid antigen 3, a proinflammatory ligand, has been shown to induce the expression of IL-6 and TNF-α, as well as ROS production, thereby promoting endothelial dysfunction." (PMID 29387042, 2018). "Further, elimination of either IL-6 or TNF-α restored the impaired redox balance between the levels of ROS and the antioxidant directly responsible for endothelial dysfunction." (PMID 29095915, 2017). "Inflammatory response acts in endothelial dysfunction appearance by means of proinflammatory cytokines, such as TNF-α, IL-6, and IL-1." (PMID 29200598, 2017). "IL-6 and TNF-α increase neutrophil superoxide anion generation that can inactivate eNO and prostacyclin (PGI2) resulting in endothelial dysfunction." (PMID 28824543, 2017). "We therefore measured the circulating levels of the main pro-inflammatory mediators that can be directly affected by Mg/Ca and by endothelial dysfunction, including TNF-α, IL-6 and CRP: they were all substantially higher in AAD patients than controls." (PMID 28070203, 2017). "Inflammatory markers namely, TNF-α, IL-6 and AGP significantly and positively correlated with each other and with ET-1, a marker for endothelial dysfunction." (PMID 28344817, 2017).
endothelial dysfunction (continued). "IL-6 promotes Ang II type 1 receptor (ATR1) gene expression and leads to Ang II-induced vasoconstriction and ROS production which ultimately results in endothelial dysfunction." (PMID 28484449, 2017). "It implicates that IL-6 and TNF-α are interactive each other to determine the endothelial dysfunction in type 2 diabetic coronary arterioles, but a further study is needed to confirm its direct relationship." (PMID 29095915, 2017). "Microalbuminuria as a marker of early renal damage reflects widespread vascular damage (microangiopathy), a pro inflammatory state (with increased levels of IL-6, TNF-α, CRP and fibrinogen) and ensuing endothelial dysfunction." (PMID 25971452, 2015). "The increased inflammatory cytokines, IL-1β, IL-6, and TNF-α, under diabetic conditions promote the progression of endothelial dysfunctions, neutrophil accumulation, and coagulation." (PMID 26633490, 2015). "Sociodemographic, inflammatory markers (IL-6, TNF-?, CRP-us), endothelial dysfunction (flow-mediated vasodilatation - FMD), body composition (DXA) and the 25-hidroxi-vitamin D parameters were analyzed." (PMID 26395776, 2015). "Generally speaking, the accumulation of visceral fat due to metabolic syndrome will lead to over-expression of adipokines, such as resistin, IL-6, and TNF-α, resulting in diminish eNOS activity, less NO generation and endothelial dysfunction." (PMID 23029112, 2012). "IL-6, rheumatoid factor titres and low GFR were independently predictive of endothelial dysfunction in RA." (PMID 15899050, 2005). "IL-6, rheumatoid factor titre and low GFR predicted endothelial dysfunction, as assessed using biomarkers." (PMID 15899050, 2005). "Our objective was to determine the role of Interleukin-6 (IL-6) and Tumor Necrosis Factor-alpha (TNF-alpha), markers of immune activation and endothelial dysfunction, in patients with preeclampsia." (PMID 16259641, 2005). "Following acute or repetitive ischemic episodes, persistent immune activation-mediated through interleukin-6 (IL-6), interleukin-1β (IL-1β), and tumor necrosis factor-α (TNF-α)-promotes endothelial dysfunction, microvascular instability, and extracellular matrix remodeling." (PMID 42195345, 2026). "Shared mechanisms include visceral adiposity, adipokine imbalance, insulin resistance, systemic cytokine activation (IL-6, TNF-α), endothelial dysfunction, oxidative stress, intermittent hypoxia, and profibrotic transforming growth factor-beta (TGF-β)–mediated pathways." (PMID 41995935, 2026). "Although this research mainly concentrated on lipid peroxidation and lipid profiles, upcoming studies ought to incorporate biomarkers of inflammation and endothelial dysfunction, like CRP, IL-6, and adhesion molecules, to thoroughly assess the anti-atherosclerotic effects of GPHWE." (PMID 40298660, 2025). "This is consistent with the known pathophysiology of hepatic IRI, where oxidative stress and the release of inflammatory mediators such as TNF-α, IL-6, and ICAM-1 lead to systemic endothelial dysfunction and infiltration of neutrophils in remote organs, including the lungs." (PMID 40429525, 2025). "Previous clinical trials have shown that liraglutide reduced albuminuria, which is thought to be a biomarker of microvascular and macrovascular endothelial dysfunction, as well as circulating levels of various inflammatory markers, including CRP, TNF‐α and IL‐6 in individuals with type 2 diabetes." (PMID 40276845, 2025). "Additionally, elevated IL-6 and CXCL8 similarly promote vascular inflammation and endothelial dysfunction, exacerbating microvascular damage despite systemic inflammation control." (PMID 41030257, 2025). "Hyperinsulinemia and dyslipidemia can activate innate immune cells, leading to the release of pro-inflammatory cytokines such as IL-1β, IL-6, and TNF-α, which in turn promote endothelial dysfunction, vascular stiffness, and sodium retention—key hallmarks of hypertension." (PMID 40944247, 2025).
endothelial dysfunction (continued). "Similarly, IL-6, a key pro-inflammatory cytokine in CKD, drives systemic inflammation and endothelial dysfunction." (PMID 40141782, 2025). "The resulting EC damage leads to an imbalance between vasodilation and vasoconstriction processes, reactive oxygen species (ROS) formation and cytokine release (IL-1, IL-6, TNF-alpha), decreased NO availability and finally endothelial dysfunction and thrombosis." (PMID 41155474, 2025). "It is well established that EAT secretes pro-inflammatory cytokines (such as IL-1β, IL-6, and TNF-α) and pro-fibrotic adipokines (such as TGF-β), which exert paracrine effects on adjacent cardiomyocytes, promoting oxidative stress, endothelial dysfunction, and fibrosis." (PMID 41294813, 2025). "Widespread endothelial dysfunction is a central pathological mechanism in dengue-related complications due to the overproduction of inflammatory mediators, such as tumor necrosis factor-alpha (TNF-α), interleukin-6 (IL-6), and interferon-gamma (IFN-γ)." (PMID 40357076, 2025). "Therefore, in cytokine storms with increased levels of IL-6 and CRP due to endothelial dysfunction and hypercoagulability, a higher prothrombotic activity and lower fibrinolytic activity were noticed." (PMID 40647684, 2025). "Elevated cytokines such as IL-6 and TNF-α exacerbate systemic inflammation, promoting endothelial dysfunction and microvascular remodeling.Furthermore, antiphospholipid antibodies contribute to thrombotic microangiopathy, resulting in vascular occlusion and ischemia." (PMID 40589745, 2025). "Although inflammatory mediators such as IL-6, TNF-α, and CRP are elevated across all three conditions, endothelial dysfunction and systemic cytokine signaling represent central converging mechanisms, linking local periodontal inflammation and metabolic dysregulation to cardiovascular complications." (PMID 41007869, 2025). "Elevated levels of IL-6, TNF-alpha, CRP, MCP-1, and endothelial dysfunction biomarkers such as oxidized HDL and soluble ICAM-1 supports the role of inflammation in the development and persistence of visceral adiposity and systemic inflammation in this population." (PMID 40722634, 2025). "Additional pro-inflammatory mediators, including TNF-α, IL-6, and IFN-γ, may further exacerbate endothelial dysfunction and microvascular inflammation." (PMID 40722702, 2025). "Additionally, CRDs reduced inflammation and endothelial dysfunction markers (CRP, IL-6, and E-selectin)." (PMID 40935153, 2025). "GERD‐induced vagal nerve activity may influence blood pressure control, while inflammation, driven by cytokines such as IL‐6 and TNF‐α, promotes endothelial dysfunction, a precursor to HTN." (PMID 40225100, 2025). "These conditions are associated with persistent immune activation and the production of pro-inflammatory cytokines, such as interleukin-6 (IL-6), tumor necrosis factor-alpha (TNF-α), and C-reactive protein (CRP), which exacerbate endothelial dysfunction and promote atherosclerotic plaque formation." (PMID 40001504, 2025). "Furthermore, lonely individuals often experience higher levels of pro-inflammatory cytokines, including interleukin-6 (IL-6) and tumor necrosis factor-alpha (TNF-α), which contribute to endothelial dysfunction and increased thrombogenic potential." (PMID 40291206, 2025). "Furthermore, inflammatory cytokines such as interleukin-6 (IL-6) and tumor necrosis factor-alpha (TNF-α) enhance endothelial dysfunction and trigger the coagulation cascade, which further adds to the hypercoagulable condition." (PMID 41377299, 2025). "Trauma triggers a systemic inflammatory response, characterized by the release of cytokines such as interleukin-6 (IL-6) and tumor necrosis factor-alpha (TNF-α), which contribute to endothelial dysfunction, increased vascular permeability, and myocardial inflammation." (PMID 40724554, 2025).